APOE (apolipoprotein E)
Diseases named in the same sentence as APOE in open-access papers (continued):
Sharing a sentence is not in itself a finding about the gene and the disease.
Alzheimer disease (continued). "Meanwhile, the fat-mass and obesity-associated (FTO) gene, strongly related to obesity, was found to be associated with risk of Alzheimer’s disease through interaction with the APOE gene, and modulates cholesterol metabolism in the central neural network." (PMID 34501469, 2021). "Among its three alleles (ε2, ε3, and ε4), the individuals carrying the ε4 allele are at a higher risk of developing AD since the ApoE ε4/ε4 genotype increases fibrinogenesis in the brain of Alzheimer’s disease patients." (PMID 33994996, 2021). "The Alzheimer’s disease polygenic risk score and APOE ε4 presence were associated to Aβ misfolding (odds ratio, 95% confidence interval: per standard deviation increase of score: 1.25, 1.03–1.51; APOE ε4 presence: 1.61, 1.04–2.49)." (PMID 33934115, 2021). "What is the association of the apolipoprotein E (APOE) ɛ4 allele with Alzheimer disease–related clinical and biomarker changes in Down syndrome?" (PMID 34228042, 2021). "The apolipoprotein E (APOE) ε4 allele is the strongest genetic risk factor for late onset Alzheimer’s disease, whilst the ε2 allele confers protection." (PMID 33397400, 2021). "For example, the E4 variant of apolipoprotein E (ApoE4), considered the main susceptibility gene for Alzheimer’s disease, leads to an accelerated breakdown of the BBB and degeneration of brain capillary pericytes." (PMID 34439797, 2021). "Apolipoprotein E (APOE) gene is a well-established susceptibility gene for the development of late-onset Alzheimer’s disease (AD)." (PMID 34483892, 2021). "Apolipoprotein E (APOE) ε4 is the single most important genetic risk factor for cognitive impairment and Alzheimer disease (AD), while lifestyle factors such as smoking, drinking, diet, and physical activity also have impact on cognition." (PMID 34061824, 2021). "The APOE ε4 allele is a strong and well-established genetic risk factor for Alzheimer's disease (AD), and the top GWAS signal in dementia with Lewy bodies (DLB)." (PMID 33613437, 2021). "In 2015, it was clearly demonstrated in a cohort of 91,726 individuals that a low-prevalence loss-of-function mutation in ABCA1 was significantly associated with low plasma apoE levels, and with high risk of Alzheimer’s disease and cerebrovascular disease." (PMID 33925284, 2021). "Another key factor which should be examined in future work is APOE genotype, a known risk factor for both Alzheimer’s disease and epilepsy." (PMID 34379638, 2021). "Studies of the oxidative/anti-oxidative status in patients with Alzheimer’s disease (AD) carrying different alleles of the apolipoprotein E (APOE) gene are currently inconclusive; meanwhile, data regarding mitochondrial DNA copy number (mtCN) remain limited." (PMID 34943074, 2021). "Several rare variants in TREM-2 have been identified to substantially increase the risk of developing late-onset Alzheimer’s disease by 2–4 times compared to the increased risk related to one copy of the ε4 allele of the APOE gene." (PMID 33578866, 2021). "From a genetic point of view, the presence of E4 variant in APOE gene increases the risk for Alzheimer disease." (PMID 34073306, 2021). "APOE (encoding apolipoprotein E) functions in lipid transport, immunoregulation, Alzheimer's disease, and cognitive function." (PMID 33410284, 2021). "Apolipoprotein E (APOE) ε4 allele carrier status is well known for its association with an increased likelihood of developing Alzheimer’s disease, but its independent role in cognitive function is unclear." (PMID 34721516, 2021). "In a later report by the same research group, subjects with the APOE ε4 allele, with an augmented risk of Alzheimer’s disease, had elevated levels of CSF ferritin and cognitive decline." (PMID 33578866, 2021).
Alzheimer disease (continued). "Several studies examining the effect of Apolipoprotein E (ApoE) isoforms, a well-established genetic risk factor for Alzheimer’s disease (AD), on the response to 56Fe irradiation have suggested that radiation exacerbates cognitive deficits in transgenic mice." (PMID 34948098, 2021). "The disagreements regarding the CA3 region are probably caused by the usage of the ApoE knockout mouse line, a suitable model to study hyperlipidemia, which is a risk factor for neurodegenerative diseases, including Alzheimer’s disease." (PMID 34587222, 2021). "In particular, the ε4 allele of APOE is the highest genetic risk factor for developing late-onset Alzheimer’s disease (AD)." (PMID 34475505, 2021). "Higher levels of CCL5 have been associated with Alzheimer’s disease (AD) in patients and the ApoE genotype; however, the link to pathology and plasticity has been little studied." (PMID 33931731, 2021). "Because there is a strong genetic association between APOE genotypes and Alzheimer’s disease, it is important to have an understanding on how genotypes interact with sex to affect individual cognitive functions as well as the underlying neural mechanisms." (PMID 32954402, 2021). "It is well established that Apolipoprotein E (ApoE) ɛ4 genotype is a genetic risk factor for Alzheimer's disease (AD)." (PMID 34555265, 2021). "The human Apolipoprotein E4 (ApoE4) variant is the strongest known genetic risk factor for Alzheimer’s disease (AD)." (PMID 34912029, 2021). "For example, APOE is the best-known genetic risk for sporadic Alzheimer’s disease but is only semi-dominant and moderately penetrant; at an age of 85 years, between 30% and 50% of APOE ε4 homozygotes do not have dementia." (PMID 33892488, 2021). "Genome-wide association studies (GWAS) have identified polymorphism in the Apolipoprotein E gene (APOE) to be the most prominent risk factor for Alzheimer’s disease (AD)." (PMID 33837271, 2021). "Approximately 25% of the general population carries at least one ε4 allele of the Apolipoprotein E (APOE ε4), the strongest genetic risk factor for late onset Alzheimer’s disease." (PMID 33397450, 2021). "Age, apolipoprotein E (apoE) isoform, sex, and diet can independently affect the risk for the development of Alzheimer’s disease (AD)." (PMID 34545146, 2021). "Assessment of the polygenic risk score and stratifying by APOE reveal a 4 to 5.5 years difference in median age at onset of Alzheimer’s disease patients in APOE ɛ4 carriers." (PMID 34099642, 2021). "Late-onset Alzheimer’s disease and patients who present with APOE E4 polymorphism show, in particular, hippocampal atrophy, whereas the central region is relatively spared." (PMID 33660199, 2021). "Pericytes can produce large quantities of APOE, various alleles of which influence cerebrovascular functions and determine the genetic risk for Alzheimer’s disease." (PMID 34497540, 2021). "APOE is a critical cholesterol and triglyceride transporter necessary for the maintenance of neuronal membranes and myelin, with APOE-e4 allele carriers being at significantly higher risk of developing Alzheimer’s disease." (PMID 33615215, 2021). "The ε4 allele of the Apolipoprotein E (APOE) gene is the strongest genetic risk factor for late onset Alzheimer’s disease (AD)." (PMID 33397450, 2021). "The strongest genetic risk factor for Alzheimer’s disease (AD) is the ε4 allele of Apolipoprotein E (APOE) and recent genome-wide association meta-analyses have confirmed additional associated genetic loci with smaller effects." (PMID 32404947, 2021). "The Ε4 allele of Apolipoprotein E (APOE) confers more risk (up to 15 fold) for the development of late-onset Alzheimer’s disease (AD) than any other gene." (PMID 34488832, 2021). "There is also acorrelation to the apolipoprotein E4 (ApoE4) allele: infection of COVID-19 is higher inApoE4 carriers who are vulnerable to Alzheimer’s disease." (PMID 34222864, 2021).
Alzheimer disease (continued). "Here again, the sample was older (mean age = 73 years), highly educated (mean = 15.8 years), and at elevated risk for Alzheimer’s disease (47.6% APOE-ε4-positive)." (PMID 34396116, 2021). "The apolipoprotein Eε4 allele (APOE4) is the major genetic risk factor for Alzheimer’s disease in humans; individuals with one or two copies of this allele have a fourfold to eightfold increased risk in developing Alzheimer’s disease." (PMID 33037985, 2021). "Genetic risk for Alzheimer’s disease (AD) takes several forms, including: Mendelian, rare, polygenic, APOE and family risk." (PMID 34301914, 2021). "BLNK assists in activation of immune cells, APOE codes for apolipoprotein associated with Alzheimer’s disease and IRF1 is activated by interferon gamma and regulates expression of antiviral genes." (PMID 34681730, 2021). "The ApoE-ε4 allele is the strongest genetic risk factor for Alzheimer’s disease, as well as atherosclerosis, and longevity." (PMID 34786016, 2021). "APOE ε4 polymorphisms are also the strongest genetic risk for late-onset Alzheimer disease (AD), whereas ε2 polymorphisms protect against AD." (PMID 33748669, 2021). "Nearly half of the subjects (n = 714) had Alzheimer’s dementia and one-fourth (n = 412) had APOE ε4 allele." (PMID 34563269, 2021). "The bridging integrator 1 (BIN1) gene is the second most important susceptibility gene for late-onset Alzheimer’s disease (LOAD) after apolipoprotein E (APOE) gene." (PMID 33531457, 2021). "Among its three alleles (ε2, ε3, and ε4), individuals carrying the ε4 allele are at a heightened risk of developing AD as the ApoE ɛ4/ɛ4 genotype increases fibrinogenesis in the brains of Alzheimer’s disease patients." (PMID 33078369, 2021). "In the CNS, ApoE regulates the clearance of amyloid beta (Aβ), which is a common hallmark of NDs, mainly associated with Alzheimer's disease (AD)." (PMID 33488947, 2021). "The apolipoprotein E (APOE) gene ε4 allele stands out as an impressive signal for the increased risk of late-onset Alzheimer’s disease, as identified in 1993 and since confirmed worldwide." (PMID 33925284, 2021). "All genetic markers were predictive of Alzheimer’s disease diagnosis albeit much less so than Aβ misfolding (areas under the curve: Aβ polygenic risk score: 0.55; AD polygenic risk score: 0.59; APOE ε4: 0.63; Aβ misfolding: 0.84)." (PMID 33934115, 2021). "The apolipoprotein E gene (APOE) is the most important genetic risk factor for sporadic Alzheimer disease, with the ε4 allele being associated with increased cerebral amyloid-β and tau pathologies." (PMID 34189460, 2021). "The APOE ε2 allele proven to be the strongest genetic protective factor but the APOE ε4 allele was the strongest genetic risk factor for Alzheimer’s disease after multiple large scale genome-wide studies." (PMID 34924994, 2021). "This is the first study to assess the effects of interaction between sex and APOE genotype, which has a strong relationship with the risk of Alzheimer’s disease in elderly individuals, on cognitive traits, and brain structure in a large sample of young adults." (PMID 32954402, 2021). "There is some evidence of genetic moderation of apathy in dementia, such as the apolipoprotein E gene (APOE) ε4 allele in Alzheimer's disease, as well as C9orf72 and GRN mutations in FTD." (PMID 33316852, 2021). "In both the direction and magnitude of the RNA‐abundance shift, the influence of Alzheimer's disease was less consistent and so appeared less pronounced on average, than that of the APOE allele." (PMID 33788386, 2021). "APOE is implicated in dyslipidemia and Alzheimer disease (AD); however, its connection with VCID is less understood." (PMID 33841127, 2021). "Numerous empirical results suggested there was an association between ApoE gene and Alzheimer's disease, between ApoE gene and lipid levels, as well as between ApoE gene and cognition." (PMID 34135129, 2021).
Alzheimer disease (continued). "The APOE-ε4 allele has significant influence on cognitive function, and APOE-ε4 homozygosity is the strongest known single risk factor for late onset Alzheimer’s dementia." (PMID 33658917, 2021). "The critical role of ApoE in neurological disorders has long been studied, with significant attention on ApoE4 as a substantial risk factor for the development of Alzheimer’s disease." (PMID 34369386, 2021). "Polymorphism in the apolipoprotein E (APOE) gene is a major risk for developing late onset Alzheimer disease (LOAD), whose symptoms are more frequently appearing after the age of 65 years." (PMID 33679311, 2021). "APOE ε4 increases the risk of Alzheimer's disease and lowers the age of disease onset in a gene-dose-dependent manner." (PMID 33763108, 2021). "APOE is important in lipoprotein metabolism and immunoregulation strongly associated with cardiovascular and Alzheimer’s disease." (PMID 34707490, 2021). "Here the authors investigate risk scores for Alzheimer’s disease, finding that the most effective approach includes an APOE score and a polygenic score excluding APOE." (PMID 34301930, 2021). "The pathological process of late-onset Alzheimer’s disease involves mitochondrial damage of neurons, oxidative stress, and apolipoprotein E (APOE) polymorphism in the vascular endothelium." (PMID 33578866, 2021). "The triggering receptor expressed on myeloid cells (TREM)-2 serves as a binding partner for apolipoprotein E (APOE,), and especially the ε4 allele has been shown to act as a risk factor for Alzheimer’s disease." (PMID 34571885, 2021). "Different studies have already proved the role of the E4 allele of APOE (Apolipoprotein E) in increasing the risk of Alzheimer’s disease." (PMID 34643772, 2021). "The APOE gene is the strongest genetic determinant of all‐cause dementia, especially Alzheimer's disease (AD), with the ε4 allele elevating risk and accelerating age of onset." (PMID 34041846, 2021). "For example, people who carry a version of the apolipoprotein E gene called APOE4 have a greater risk of developing Alzheimer’s disease or heart disease." (PMID 34586066, 2021). "Here we report how four major forms of Alzheimer’s disease (AD) genetic risk—APOE-ε4, APOE-ε2, polygenic risk and familial risk—are associated with 273 traits in ~500,000 individuals in the UK Biobank." (PMID 34301914, 2021). "The apolipoprotein E4 (ApoE4) allele has been identified as a major risk factor for Alzheimer’s Disease (AD)." (PMID 32632205, 2021). "Polymorphisms in the apolipoprotein E (ApoE) gene confer a major genetic risk for the development of late-onset Alzheimer’s disease (AD) and are predictive of outcome following traumatic brain injury (TBI)." (PMID 34795427, 2021). "The E4 variant of apolipoprotein E (APOE4) is a well-known strong genetic risk factor for Alzheimer’s disease (AD) and confers susceptibility to MCI." (PMID 34780525, 2021). "In spite of evidence of females having a greater lifetime risk of developing Alzheimer’s Disease (AD) and greater apolipoprotein E4-related (APOE ε4) AD risk compared to males, molecular signatures underlying these differences remain elusive." (PMID 34658838, 2021). "Alzheimer’s disease (AD) is the most common neurodegenerative disorder and the presence of the APOE ε4 allele is the major genetic risk factor for the disease." (PMID 33600562, 2021). "For example, APOE gene polymorphism is significantly associated with the development of Alzheimer’s disease (AD)-like dementia after TBI." (PMID 34685663, 2021). "Cerebral glucose hypometabolism is consistently observed in individuals with Alzheimer’s disease (AD), as well as in young cognitively normal carriers of the Ε4 allele of Apolipoprotein E (APOE), the strongest genetic predictor of late-onset AD." (PMID 34488832, 2021).
Alzheimer disease (continued). "Presence of ApoE4 allele is a major risk factor for developing Alzheimer’s disease (AD) and other disorders late in life, but the mechanisms responsible for biological differences between different ApoE isoforms are not well understood." (PMID 34068576, 2021). "ApoE-ε4 is a risk factor for a variety of diseases, such as Alzheimer’s disease (AD), cardiovascular disease, and hyperlipidemia." (PMID 34867826, 2021). "The identification of an association between individuals carrying the epsilon 4 allele of apolipoprotein E (APOE4) gene and an elevated risk of late-onset Alzheimer’s disease (AD) has been widely observed in population groups of various ethnicities." (PMID 34943074, 2021). "Apolipoprotein E4 (ApoE4) is the most important and prevalent risk factor for late-onset Alzheimer’s disease (AD)." (PMID 34617884, 2021). "It has been well-established that polymorphism in the APOE gene is one the strongest genetic predictors of sporadic Alzheimer’s disease (AD) risk." (PMID 33837271, 2021). "Apolipoprotein E (ApoE) epsilon 4 haplotype (e4) is the major risk factor for the Alzheimer disease (AD)." (PMID 33804213, 2021). "Apolipoprotein E (APOE) genotype has a well-established association with susceptibility to Alzheimer Disease, with the APOE ε4 allele associated with both AD risk and lower age at disease onset." (PMID 34068064, 2021). "LDL receptors are related to Alzheimer’s disease (AD) pathogenesis as receptors of apolipoprotein E (apoE), being the APOE4 variant the largest known genetic risk factor for late-onset sporadic AD." (PMID 34727970, 2021). "Studies examining the effect of polygenic risk scores (PRS) for Alzheimer's disease (AD) and apolipoprotein E (APOE) genotype on incident dementia in very old individuals are lacking." (PMID 33532541, 2021). "Baseline participant characteristics as stratified by Apolipoprotein E (APOE) genotype (ε4-/ε4+) and Alzheimer’s disease genetic risk score (AD-GRS; Clusterin + Complement receptor 1+ Phosphatidylinositol-binding clathrin assembly protein)." (PMID 34603005, 2021). "In order to evaluate if our cohort is enriched with AD patients, we assessed the frequency of the ApoE alleles given that ApoE4 is associated with an increased risk of Alzheimer’s disease." (PMID 34561610, 2021). "The apolipoprotein E (ApoE) ε4 genotype is associated with dementia, and the ε4ε4 (homozygous) genotype is associated with a 14-fold increase in the risk of Alzheimer's disease (AD) compared to the common ε3ε3 genotype." (PMID 34335338, 2021). "With phenotypes like Alzheimer’s disease, which have a strong and well-established genomic locus (APOE), the cumulative effect of genetic variants outside of this area has not been well established in a population-representative sample." (PMID 33143703, 2020). "There are three APOE polymorphic alleles in humans (e2, e3, and e4) that are the leading genetic markers for Alzheimer’s disease (AD)." (PMID 31991879, 2020). "In a large number of neuropathologically confirmed cases and controls, the impact of different APOE genotypes on Alzheimer’s dementia risk was greater than previously thought and APOE2 homozygotes had an exceptionally low risk." (PMID 32015339, 2020). "For comparison, voxel-wise analyses for APOE ɛ4 showed only modest focal medial temporal signal, in contrast to the robust Alzheimer’s disease pattern of association seen for the PPP2R2B and IGF2BP3 SNPs identified through GWAS." (PMID 33426524, 2020). "In humans, ApoE is found in three commonly occurring protein alleles with ApoE3 considered the “wildtype” form as it is most predominant in humans and is Alzheimer’s disease risk-neutral." (PMID 32119690, 2020). "Studies show that the APOE Ԑ4 isoform is associated with an increased risk of Alzheimer’s disease and the APOE Ԑ2 isoform is associated with a decreased risk of Alzheimer’s disease." (PMID 32100327, 2020).